PYGO1 (pygopus family PHD finger 1)
Description:
Involved in signal transduction through the Wnt pathway.
Tractability: No criterion of Open Targets' tractability assessment is met for any kind of drug.
Gene: Protein-coding gene on chromosome 15 (55,538,884 to 55,588,947, reverse strand). Ensembl gene ENSG00000171016.
Subcellular location: Nucleus
Subcellular location (Human Protein Atlas): Nucleoplasm; Cytosol
Pathways (Reactome):
Signal Transduction: Deactivation of the beta-catenin transactivating complex; Formation of the beta-catenin:TCF transactivating complex
Gene Ontology:
Molecular function: histone H3K4me3 reader activity; protein binding
Biological process: kidney development; spermatid nucleus differentiation; canonical Wnt signaling pathway; chromatin organization
Cellular component: nucleoplasm; nucleus
Genetic constraint (gnomAD): Loss-of-function variants: 5 observed, 27.88 expected, observed/expected ratio (o/e) 0.18, 90% interval 0.093 to 0.38. The upper end of that interval is the gene's LOEUF score, 0.38, which puts it in group 1 of 6, group 1 being the genes least tolerant of losing a copy. Missense variants: 515 observed, 533.93 expected, observed/expected ratio (o/e) 0.96, 90% interval 0.9 to 1.04. Synonymous variants: 186 observed, 186.43 expected, observed/expected ratio (o/e) 1, 90% interval 0.88 to 1.13.
Homologues: Orthologues: chimpanzee PYGO1 (99% identical), macaque PYGO1 (99% identical), rabbit PYGO1 (97% identical), dog PYGO1 (97% identical), pig PYGO1 (96% identical), guinea pig PYGO1 (91% identical), mouse Pygo1 (89% identical), rat Pygo1 (89% identical), zebrafish pygo1 (41% identical), Drosophila melanogaster pygo (25% identical), Caenorhabditis elegans pygo-1 (18% identical). Paralogues in human: PYGO2 (34% identical).
Diseases named in the same sentence as PYGO1 in open-access papers:
PYGO1 is named in the same sentence as 12 diseases in open-access papers, as found by Europe PMC text mining. Sharing a sentence is not in itself a finding about the gene and the disease. The quoted sentences say what the papers report.
colorectal cancer (2 papers, 2008 to 2019). A primary or metastatic malignant neoplasm that affects the colon or rectum. "For example, PYGO1 is involved in colorectal cancer, while PYGO2 was shown to be a tumor promoter in mice." (PMID 31568528, 2019).
steatosis (2 papers, 2021 to 2022). Increased lipid within the cytoplasm of cells. "An intronic variant near the LEPR gene was associated with NASH at genome-wide significance, and a missense variant in PYGO1 encoding p.P299H (rs11858624) was associated with protection from steatosis at close to genome-wide significance." (PMID 34950105, 2021). "PYGO1 has only been associated with histologically identified steatosis." (PMID 34950105, 2021). "Recently, a GWAS identified a new signal on chromosome 15 (rs11858624) in the Pygopus family PHD finger 1 (PYGO1) gene, a novel steatosis modifier that contributes to the Wnt signaling pathway, suggesting that Wnt signaling pathways may be relevant in NAFLD/NASH pathogenesis." (PMID 35739957, 2022).
adenoma (1 paper, 2016). A neoplasm arising from the epithelium. "We have previously shown that Pygo2, but not Pygo1, is overexpressed in different stages of human colon cancer and in adenoma of APCMin/+ mice." (PMID 27811361, 2016).
lung carcinoma (1 paper, 2022). "The overexpression of Pygo1 in lung cancer cells in vitro promoted cancer cell proliferation and migration, but inhibited cell apoptosis." (PMID 36398031, 2022). "Overexpression of Pygo1 in lung cancer cells resulted in enhanced G1/S cell phase transformation, reduced apoptosis, and increased cell proliferation." (PMID 36398031, 2022). "Our current observations also suggested that Wnt/β-catenin partially mediated the migration of Pygo1 to lung cancer cells." (PMID 36398031, 2022). "Migration, wound healing, and colony formation assays revealed that Pygo1 overexpression enhanced the invasion and migration of lung cancer cells, increased the formation of clones, and suppressed E-cadherin expression." (PMID 36398031, 2022). "Our results supported a positive correlation between Pygo1 expression and the nuclear β-catenin level in lung cancer patients, indicating that Pygo1 induced lung cancer through a β-catenin-dependent mechanism." (PMID 36398031, 2022). "In addition, overexpression of Pygo1 in lung cancer cells led to an increase of β-catenin/TCF4 complex, as well as upregulated expression of target genes of β-catenin." (PMID 36398031, 2022). "KYA1797K also eliminated the effects of Pygo1 overexpression on lung cancer cell proliferation, apoptosis, colony formation, and tumor formation inside the body, suggesting that Pygo1 played an extensive and canonical Wnt pathway-dependent role in lung cancer." (PMID 36398031, 2022). "To investigate whether Pygo1 regulates Wnt signaling pathway transcriptional activity in lung cancer cells, we then evaluated the levels of β-catenin in Pygo1 overexpressed A549 cells." (PMID 36398031, 2022). "Interestingly, Pygo1 promotes cancer through Wnt/β-catenin signaling, which seems to occur in human lung cancer patients." (PMID 36398031, 2022). "Moreover, in vitro data showed that Pygo1 promoted lung cancer, induced cell cycle transformation, and inhibited apoptosis, which led to an expansion of the cell population." (PMID 36398031, 2022). "In addition, our in vitro data also showed that Pygo1 promoted lung cancer cell clone formation and migration, suggesting that this protein might also regulate tumor metastasis." (PMID 36398031, 2022). "Moreover, in vitro experimental data showed that overexpression of Pygo1 in lung cancer cells could promote β-catenin/TCF4 complex formation." (PMID 36398031, 2022). "However, little is known about the role of Pygo1 in human lung cancer." (PMID 36398031, 2022). "However, the role of the homolog Pygo1 in human lung cancer remains unclear." (PMID 36398031, 2022). "The consistent upregulated expression of Pygo1 in LUAD I, LUAD II, and LUSC III tissue samples suggested that Pygo1 might be closely related to the occurrence of lung cancer." (PMID 36398031, 2022). "Here, we attempted to explore whether Pygo1 participates in abnormal activation of Wnt signaling pathway I in human NSCLC and whether the interaction between Pygo1 and β-catenin affects lung cancer development." (PMID 36398031, 2022). "In conclusion, Pygo1 affects human NSCLC via the canonical Wnt/β-catenin pathway, which provides new clues for lung cancer pathology." (PMID 36398031, 2022).
tumor (3 papers, 2019 to 2022). "In vivo experiments also revealed that Pygo1 overexpression promoted the tumorigenicity of a xenograft tumor model, while Wnt inhibition partially blocked the effect of Pygo1 overexpression." (PMID 36398031, 2022). "Taken together, our results demonstrated that Pygo1 exerted a wide range of cell biological functions in tumorigenesis and tumor development." (PMID 36398031, 2022). "Moreover, the xenograft model experiments demonstrated that overexpression of Pygo1 promoted tumor formation." (PMID 36398031, 2022). "Our RNA profiling data suggested that Bcl9 loss contributed rather more than Pygo loss to the QKO-dependent trend reversals, perhaps explaining why the tumour phenotypes of the QKO mice resembled those of Bcl9/B9l rather than Pygo1/2 DKO." (PMID 30760710, 2019).
cancer (1 paper, 2022). A tumor composed of atypical neoplastic, often pleomorphic cells that invade other tissues. "Immunohistochemical analysis was consistent with the in vitro results; that is, high β-catenin signal in cancer tissues was accompanied with high expressing levels of Pygo1." (PMID 36398031, 2022). "In addition, the immunohistochemical staining of cancer tissue sections further confirmed the increased expression of Pygo1 in NSCLC." (PMID 36398031, 2022).
PYGO1 also shares sentences with these, for which no sentence is quoted: colon cancer (1 paper); congenital heart defects (1); intestinal tumors (1); liver disorder (1); non-alcoholic fatty liver (1); non-small cell lung carcinoma (1).